SOX2 (SRY-box transcription factor 2)
Diseases named in the same sentence as SOX2 in open-access papers (continued):
Sharing a sentence is not in itself a finding about the gene and the disease.
embryonal carcinoma (continued). "Overall, when tumor cells simultaneously express CD30, SOX2, OCT4 and SALL4, the diagnosis of extragonadal embryonal carcinoma is almost certain." (PMID 37138865, 2023). "Several studies have shown potential interaction between SOX2 and MTA1/2/3, MBD2, GATAD2A/B, and HDAC1/2 in different cell lines, including embryonic stem cells, neural stem cells, and embryonal carcinoma cells." (PMID 35615634, 2022). "We further identified two pivot AS-related molecules (SOX2 and HDAC9) involved in AS regulation, which were validated in embryonal carcinoma and seminoma cell lines." (PMID 36713456, 2022). "Experimentally, we showed that transfection of MIR630 mimic into embryonal carcinoma cell lines directly targeted the 3′UTR of OCT4, SOX2, and NANOG and markedly suppressed their expression." (PMID 35008480, 2021). "Luc-reporters containing CRMs bound by SOX2 specifically in the CNS were activated in an additive fashion by SOX2 and OTX1 misexpression in mouse embryonic carcinoma P19 cells." (PMID 29432416, 2018). "In agreement with the PCR data, the levels of Sox2 protein were also clearly elevated in MCF-7TamR cells, although they were lower than Sox2 levels in undifferentiated human embryonal carcinoma stem cells (NTera2/D1 cell line)." (PMID 24178749, 2014). "In contrast, when human embryonal carcinoma-derived (hEC) 2102Ep cells were treated with sodium butyrate, they continued to express high levels of SSEA-3, SSEA-4, NANOG, OCT4, and SOX2." (PMID 24707296, 2014). "As such, SOX2 is an oncogenic transcription factor and crucial cancer stem cell (CSC) biomarker in embryonal carcinoma and, as more recently found, in the stem-like cancer cell component of many other malignancies." (PMID 25156079, 2014). "The motifs have been shown to bind Sox2, Oct4 and Oct1 in vitro and can drive demethylation of partially methylated ICR transgenes in a mouse embryonic carcinoma cell line." (PMID 24324735, 2013). "SOX2 expression is predominantly restricted to embryonic carcinoma, followed by mixed germ cell tumors and one case of yolk sac tumor, whereas SOX17 is mainly in seminoma with several cases of mixed germ cell tumors and one case of embryonic carcinoma." (PMID 39996497, 2025). "We found that like in the MGG8TPC, SOX2 is expressed in mouse brain tissue and P19 embryonic carcinoma cells but not in HEK293 cells." (PMID 33692826, 2021). "By contrast, hESCs and embryonic carcinoma cells exhibit CD30 (also known as TNFRSF8) and SOX2." (PMID 25543152, 2015). "Distinction between seminoma and embryonal carcinoma could therefore be made by the expression of SOX17/CD38 and SOX2/CD30, respectively." (PMID 25543152, 2015). "In control experiments and as expected, strong SOX2 staining is seen in all nuclei of F9 embryonal carcinoma cells, but is absent from hepatocyte cells demonstrating the specificity of this staining." (PMID 24498316, 2014). "SOX2 is highly expressed in embryonal carcinoma (EC), the stem cell component of malignant nonseminomatous germ cell tumors, referred to as germ cell cancer (GCC)." (PMID 24404135, 2014). "Meanwhile, SOX2 knockout in an embryonic carcinoma cell, NCCIT, with the same gSOX2, resulted in a reduced self-renewal ability, as assessed by the alkaline phosphatase staining assay, suggesting that gSOX2 functionally affects the stemness of embryonic carcinoma cells." (PMID 38334608, 2024). "LSD1-blocking compounds are known to differentially target pluripotent cancer cells including teratocarcinoma, embryonic carcinoma, and seminoma, or embryonic stem cells that express SOX2, while having minimal growth-inhibitory effects on non-pluripotent cancer or normal somatic cells." (PMID 32191225, 2020). "Numerous studies have demonstrated that the regulatory regions of SOX2 are nonmethylated during the course of neural differentiation of embryonal carcinoma cells suggesting that the changes of SOX2 expression during neural differentiation are independent of DNA methylation." (PMID 28886103, 2017).
embryonal carcinoma (continued). "Current models of GCT differentiation suggest that embryonal carcinoma and seminoma are the undifferentiated types of tumors and that they share many features with normal embryonic stem cells including expression of pluripotency factors such as NANOG, POU5F1, and SOX-2 among others." (PMID 24475288, 2014). "Positive staining for CD30, OCT3/4, NANOG, SOX2 GP-3, or CD30 tends to occur more commonly among embryonal carcinomas while negative staining occurs more commonly among yolk sac tumors, serving as reliable indicators between them both neoplasms." (PMID 37443818, 2023). "Western blot analysis verified the presence of OCT4, SOX2 and NANOG in hiPSCs and NT2 cells (pluripotent embryonal carcinoma cells, as a positive control), as well as the absence of α-SMA and GFAP." (PMID 30518391, 2018). "To extend the generality of these findings to other pluripotent cells, we overexpressed p27 in murine P19 embryonal carcinoma (P19EC) cells at levels that did not affect proliferation and found a significant decrease of Sox2 mRNA levels." (PMID 23217425, 2012).
head and neck squamous cell carcinoma (50 papers, 2015 to 2025). A squamous cell carcinoma that arises from any of the following anatomic sites: lip and oral cavity, nasal cavity, paranasal sinuses, pharynx, larynx, and salivary glands. "Additionally, it has been shown that not only the loss of KLK6 but also the loss of SOX2 expression induces cell motility via vimentin up-regulation and is an unfavorable risk factor for survival of head and neck squamous cell carcinoma." (PMID 28671620, 2017). "SOX2 is upregulated in head and neck squamous cell carcinoma (HNSCC) due to the enhancing effect of TAMs on the availability of HA, which binds to CD44 receptors on the surface of cancer cells." (PMID 38331879, 2024). "The SOX2 gene located at 3q26 is frequently amplified and overexpressed in multiple cancers, including head and neck squamous cell carcinomas (HNSCC)." (PMID 30823625, 2019). "SOX2 can predict prognosis for head and neck squamous cell carcinoma, and its expression also can be associated with an advanced tumor stage in adenoid cystic carcinoma of the head and neck." (PMID 30186173, 2018). "SOX2 was reported to regulate STING expression in head and neck squamous cell carcinoma." (PMID 35415876, 2022). "Furthermore, OTSSP167 has been shown to suppress Sox2 expression in a dose-dependent manner in head and neck squamous cell carcinoma (HNSCC)." (PMID 31861475, 2019). "In the primary tissue of head and neck squamous cell carcinoma (HNSCC) patients, expression of SOX2 is abnormal but stays standard in healthy tissue." (PMID 35008527, 2021). "The Rickman Head and Neck Cancer gene set is positively correlated with POU5F1 and SOX2 gene expression and consists of genes identifying an intrinsic group in head and neck squamous cell carcinoma (HNSCC)." (PMID 32899474, 2020). "Recently, two studies reported that high expression level of Sox2 in head and neck squamous cell carcinomas (HNSCC) had beneficial effect on patient survival." (PMID 29228716, 2017). "A recent study reported that inhibiting FAK, a protein found in head and neck squamous cell carcinoma (HNSCC), could significantly reduce the expression of stem cell markers, including Oct4, Sox2, and Nanog, leading to a decrease in cell self-renewal." (PMID 37749625, 2023). "PSMD14 overcame drug resistance in head and neck squamous cell carcinoma by inhibiting E2F1 ubiquitination and degradation, improving Akt pathway activation and SOX2 transcription." (PMID 37349676, 2023). "There is evidence that overexpression of c-fos in head and neck squamous cell carcinoma enhances epithelial-mesenchymal transition (EMT) and the expression of cancer cell markers (Nanog, c-Myc, Sox2 and Notch1)." (PMID 33096691, 2020). "For instance, AFF4 could upregulate SOX2 transcription to promote the tumor-initiation capacity of head and neck squamous cell carcinoma (HNSCC), and MYC is another known target of AFF4." (PMID 32676121, 2020). "Several CSC markers have been studied in head and neck squamous cell carcinomas (HNSCC), including the pluripotency factors NANOG, SOX2, and OCT4; however, their clinical significance is still unclear." (PMID 32635524, 2020). "For instance, KLF7 binds to the IGF2BP2-SE to drive IGF2BP2 overexpression and promote tumor progression in head and neck squamous cell carcinoma (HNSCC), while TP63 and SOX2 co-activate SEs and the promoter of CCAT1 to drive tumorigenesis in squamous cell carcinomas (SCCs)." (PMID 41462308, 2025). "In head and neck squamous cell carcinoma, PSMD14 can influence tumor cell proliferation, drug resistance, and cell stemness by blocking E2F1 ubiquitination and degradation, boosting Akt pathway activation, and promoting SOX2 transcription." (PMID 38053170, 2023). "Vice versa, the robust effect of AKT inhibition on SOX2 protein expression that we document here for BC was not consistently observed in other tumor-derived cell types, e.g. in ovarian or squamous head and neck cell carcinoma lines." (PMID 26498353, 2015).
head and neck squamous cell carcinoma (continued). "The early transcription factors NANOG, OCT4, and SOX2, which play pivotal roles in the maintenance of pluripotency and self-renewal ability in both embryonic and adult stem cells, have also been reported as key regulation factors in the CSCs of head and neck squamous cell carcinoma (HNSCC)." (PMID 26626427, 2015). "Additionally, in head and neck squamous cell carcinoma (HNSCC), ZSCAN4 played an important role in facilitating chromatin remodeling and activating cancer stem cell factor expression, including OCT3/4, NANOG, KLF4, and SOX2." (PMID 36841776, 2023). "Notch1 also appears to critically regulate stemness in head and neck squamous cell carcinoma (HNSCC) cells, as constitutive activation of NICD in HNSCC cells promotes self-renewal by enhancing tumorsphere formation and upregulating stemness markers such as OCT4, SOX2, and CD44." (PMID 36118530, 2022). "Similarly, in head and neck squamous cell carcinoma (HNSCC), TAZ enhances cancer stemness by activating the transcription factor SOX2." (PMID 39900917, 2025). "Similarly, in head and neck squamous cell carcinoma (HNSCC), PSMD14 decreased E2F1 ubiquitination and degradation, which improved AKT pathway activation and SOX2 transcription, thereby facilitating HNSCC growth, chemoresistance, and stemness." (PMID 36959615, 2023). "RhoC knockdown in HNSCC (Head and Neck Squamous Cell Carcinoma) showed a defect in activation of STAT3 in the cells and therefore a reduction in the expression of core stem cell markers like Oct3/4, Sox2, and Nanog." (PMID 27597870, 2016).
breast tumor (46 papers, 2011 to 2025). "Moreover, Pearson correlation analysis demonstrated that PLA2G16 was positively associated with CSC-related gene (e.g., Sox2 and Oct4) expression in breast tumor tissues." (PMID 34715882, 2021). "The embryonic stem cell factor Sox2, implicated in development, pluripotency, and cancer biology, is also found in breast stem/progenitor cells and is highly expressed in breast tumors that have developed resistance to endocrine therapy and display poor clinical outcome." (PMID 32290242, 2020). "The 4T1 mouse cancer cell line derived from BALB/c mouse BC cells can be used as an orthotopic syngeneic breast tumor mouse model to demonstrate the expression of pAkt, Akt, and Sox2." (PMID 40076435, 2025). "To test this idea, we overexpressed or reduced KLF8 expression in MDA-MB-231 and SUM159 cells and assessed mRNA and protein expression of major stem cell factors that are associated with breast tumor development and include OCT4, SOX2, NANOG and c-MYC." (PMID 37152043, 2023). "Elevated expressions of IL20RA and SOX2 in breast tumor tissues were detected when compared to the matched para-carcinoma tissues." (PMID 33456560, 2021). "A positive correlations among the levels of p-ATM, SOX2, and acetyl-CoA products was found in 92 clinical breast tumors." (PMID 32641713, 2020). "Breast tumors that have developed resistance to hormone therapy display increased Sox2 expression, which supports its potential as a biomarker of resistance to therapy." (PMID 32290242, 2020). "We have found that tamoxifen-resistant cells are enriched for CSCs and express high levels of the stem cell marker Sox2, which is also expressed in normal breast stem cells, although at lower levels than in breast tumor cells." (PMID 32290242, 2020). "SOX2 plays an important role in carcinogenesis of early stage breast tumors and possibly promotes tumor metastasis as metastatic lymph nodes were reported to enrich in SOX2 expression." (PMID 30517668, 2020). "Snail overexpression greatly enhanced tumor growth, whereas Sox2 or VEGF knockdown inhibited breast tumor growth." (PMID 32541667, 2020). "Xenograft studies in NUDE mice demonstrated stable SOX2 repression and long-term breast tumor growth inhibition, which lasted for >100 days post implantation of the tumor cells in mice." (PMID 25684141, 2015). "The immunohistochemistry results indicated a correlation between the expression of LIN28, SOX2 and β-catenin protein and later-stage breast tumors." (PMID 26460550, 2015). "We have recently shown that the embryonic stem cell markers NANOG, OCT4 and SOX2 are expressed in normal breast stem cells and at higher levels in breast tumour cells and that their expression is reduced during cell differentiation." (PMID 24178749, 2014). "Two different breast tumor cell lines and a prostate tumor cell line each exhibit decreases in cell proliferation when SOX2 levels are elevated in the cell population from an inducible promoter." (PMID 22937156, 2012). "Additionally, based on RNA-Seq from the TCGA database, we revealed a significant positive correlation between NSDHL and SOX2 in the luminal breast tumor tissues of patients." (PMID 39516821, 2024). "Taken together, we have shown that Sox2 behaves heterogeneously in breast tumor cell populations." (PMID 25380620, 2014). "In the current study, breast tumor samples were examined for expression of SOX2 (short for Sex determing Region Y - box 2), a High Mobility Group (HMG) domain transcription factor located at chromosome 3q26.33 and member of the SRY-related HMG-box (SOX) family of transcription factors." (PMID 21276239, 2011).
breast tumor (continued). "However, SOX2 expression was detected in a subgroup of patients with breast tumors, supporting the notion that in the breast, activation of SOX2 is part of the malignant progression." (PMID 21276239, 2011). "Moreover, high Snail and Sox2 expression markedly promoted breast tumor growth." (PMID 32541667, 2020). "Because SOX2-overexpressing cells are particularly sensitive to LSD1 inhibitors, we explored the possibility that SOX2 expression might associate with the luminal entity across breast tumor subtypes." (PMID 32191225, 2020). "Similarly, elevation of SOX2 in prostate and breast tumor cells reduced the number of viable cells." (PMID 25340937, 2014). "Analyses of Hippo pathway markers in patient samples revealed that compared to their respective normal tissues, enhanced expressions of YAP/TAZ and the stemness markers, SOX2 and ALDH1A1, were observed in both naïve and chemotherapy-treated breast tumors." (PMID 39979255, 2025). "Remarkably, lncROPM was positively correlated with Sox2, Oct4, and ALDH1A1 expression in breast tumor tissues." (PMID 34715882, 2021). "Also, estrogen receptor α could regulate breast tumor-initiating cells targeting Sox-2." (PMID 28088791, 2017). "Previous studies have reported that SOX-2 is a CSC marker, which is used to identify and characterize CSCs in a variety of tumors including breast tumor." (PMID 29383157, 2017). "Previous work from our laboratory and others had shown that Sox2 gene is activated in the early phases of breast tumor development and necessary for tumorigenicity of MCF7 cells; therefore, a reporter based on Sox2 promoter elements seemed appropriate." (PMID 25414831, 2014). "Moreover, ALDH+ cells isolated from patient breast tumors exhibited elevated expression of YAP, TAZ, and SOX2, concomitant with enhanced interaction between YAP/TAZ, YAP/SOX2 and TAZ/SOX2 in the nucleus." (PMID 39979255, 2025). "Furthermore, compared to naïve tumors, higher expression of SOX2, YAP, and TAZ was observed in chemo-treated patient breast tumors." (PMID 39979255, 2025). "Interestingly, YAP/TAZ and SOX2 were found to be significantly upregulated in the CD44+/CD24− and ALDH+ population isolated from patient breast tumors, adherent cells and mammospheres." (PMID 39979255, 2025). "In the SQ breast tumors, we observed significantly upregulated mRNA levels of the Oct3/4 regulatory network, including ONSS, and several other PTFs, including Nanog, Sall4, Sox2, Sox4, FoxA2, Gata6, Zic2 and HoxB7, as well as Oct3/4 isoform B, polycomb suppressors Bmi1, EzH2, Amigo and Dkk1." (PMID 37298091, 2023). "The existing body of research on SOX‐2, OCT‐4 and NANOG suggests that early‐stage breast tumors exhibit SOX‐2 expression, with no expression of OCT‐4 and NANOG." (PMID 34914196, 2022). "In addition to ALDH1-expressing MCSCs, embryonic stem cells (ESCs) are a distinct subset of MCSCs that express embryonic transcription factors like SOX2/OCT4 and are upregulated in aggressive breast tumors." (PMID 33414685, 2020). "Moreover, we compared FOXO3a, FOXM1, SOX2, and DNMT1 expression in a tissue microarray containing 100 independent primary breast tumor samples and 32 adjacent normal breast tissues by immunohistochemistry." (PMID 31296961, 2020). "As for MCF-7, our results are in line with Sox2 and Bmi1 transcripts, but not nuclear ERα, being increased in Col-I-enriched ER+ murine breast tumors." (PMID 32435546, 2020). "Finally, Pep2–Ae enhanced the activity of AKT1 and FOXO1, and reduced the expression of FOXO1 and SOX2 in MMTV-PyMT MEC-derived breast tumors and PDX-derived breast tumors." (PMID 31844113, 2019). "However, cotreatment with both MEC plus SB 203580 was more effective in further reducing tumor volumes as well as attenuating protein expression of both SOX2 and vimentin, suggesting a casual role of both nicotine and p38 MAPK in NIC plus HFD-induced breast tumor progression." (PMID 33414685, 2020).